POMC (proopiomelanocortin)
Diseases named in the same sentence as POMC in open-access papers (continued):
Sharing a sentence is not in itself a finding about the gene and the disease.
tumor (continued). "This case supports the utility of POMC measurements in the differential diagnosis of CS and the use of advanced nuclear imaging for tumor localization." (PMID 37908478, 2023). "Four of the differentially expressed miRNAs, hsa-miR-9-3p, hsa-miR-9-5p, hsa-miR-27a-3p and hsa-miR-6506-3p, are correlated with POMC expression level in tumor tissue." (PMID 35270010, 2022). "This receptor increases POMC transcription, ACTH secretion, and tumor cell growth through the mitogen-activated protein kinase/extracellular signal-regulated kinase (MAPK/ERK) pathway." (PMID 33986726, 2021). "The administration of POMC determined melanogenic differentiation and reduced tumor growth by inducing apoptosis." (PMID 34068618, 2021). "Treatment with TBR-760 completely arrested established tumor growth in heterozygous POMC KO mice as compared with the substantial growth observed in vehicle-treated mice over the 8-week treatment period." (PMID 32591776, 2020). "In EAS, there is often incomplete processing of POMC by the tumor, resulting in high serum levels of ACTH precursors." (PMID 32903471, 2020). "The impact of TBR-760 suppression of NFPA growth in the POMC KO mouse was further demonstrated by the prevention of tumor-induced mortality." (PMID 32591776, 2020). "Retinoic acids inhibit the transcription of POMC in corticotroph tumor cells, making the drug a candidate for treatment of Cushing disease." (PMID 33066652, 2020). "Cancer-induced changes in energy balance offer an opportunity to modulate relevant neural circuits (e.g., AgRP, POMC, HO) to not only improve quality of life, but reduce energy availability to the tumor." (PMID 31174326, 2019). "After it was shown to be involved in reducing ACTH secretion and tumor growth in in vitro and animal models via inhibition of POMC expression in corticotroph tumors, RA, a nuclear receptor ligand, has been considered another potential option for CD treatment." (PMID 29915558, 2018). "POMC expression decreased in tumours in vivo after repeated irradiation and decreased POMC was also found in irradiated tumour cells in vitro." (PMID 26848743, 2016). "We have previously identified neuroendocrine and epithelial phenotypes in SCLC tumours and the neuroendocrine marker, pro-opiomelanocortin (POMC), correlated with worse overall survival in patients." (PMID 26848743, 2016). "Sections from all tumours are shown in S2 Fig Positive pixel analysis across all tumours confirmed that there were 23% more strongly positive POMC cells in the untreated tumours than in the 20Gy irradiated tumours." (PMID 26848743, 2016). "In the current study, irradiation of DMS 79 cells in vivo resulted in decreased POMC in the blood, and decreased POMC protein and mRNA expression levels in tumours even though the tumours had regrown." (PMID 26848743, 2016). "Circulating POMC accurately mimicked tumour progression in untreated xenografted mice and there was a strong correlation (r = 0.82)." (PMID 26848743, 2016). "When tumours were locally irradiated for 3 and 5 days there was also a strong positive correlation between tumour size and circulating POMC." (PMID 26848743, 2016). "In experimental studies involving AtT-20 pituitary ACTH-secreting tumor cells, retinoic acid was shown to reduce ACTH secretion in vitro by inhibiting the transcriptional activity of the transcription factors AP1 and Nur on the POMC gene, which encodes ACTH." (PMID 27034666, 2016). "Following repeated localised irradiation in vivo, circulating POMC decreased (p< 0.01), in parallel with a decrease in tumour size, but remained low even when the tumours re-established." (PMID 26848743, 2016). "The excised tumours displayed reduced and distinctly heterogeneous expression of POMC compared to untreated tumours." (PMID 26848743, 2016). "In untreated animals, POMC in the blood closely mirrored tumour growth; an ideal characteristic for a circulating biomarker." (PMID 26848743, 2016).
tumor (continued). "In cultured human and canine corticotroph tumors, gefitinib (an EGFR tyrosine kinase inhibitor) attenuated POMC expression, inhibited corticotroph tumor cell proliferation, and induced apoptosis." (PMID 23673515, 2013). "The levels of β-END, CRF, and IL-1β were analyzed by ELISA; immunohistochemistry was performed to detect the expressions of β-END, POMC, and μ-OR in the tumor and adjacent tissue." (PMID 24187573, 2013). "Other studies with implantation of tumor-derived cell lines, like AtT-20 or AtT20/hENK, Neuro2A, Neuro2A/POMC, or P19, that overexpress opioid peptides have been attempted, but such grafts would also carry the risk of tumor formation." (PMID 22745903, 2012). "Chromaffin cells expressing the ACTH precursor gene POMC were identified within the tumor cell population, suggesting that these cells may represent the source of ectopic ACTH production." (PMID 42074262, 2026). "The POMC gene was markedly overexpressed across all ACTH-secreting tumor samples." (PMID 40002253, 2025). "Moreover, Blocking EGFR activity in mice attenuated POMC expression, inhibited corticotroph tumor cell proliferation, and induced apoptosis." (PMID 38862897, 2024). "Gefitinib suppressed tumor POMC expression and downstream EGFR tumor signaling." (PMID 38862897, 2024). "Lapatinib treatment of corticotroph tumor cells decreased POMC mRNA and ACTH levels." (PMID 34867776, 2021). "Gain-of-function mutations of ubiquitin-specific protease (USP) 8, USP48, and BRAF genes may subsequently cause overexpression of epithelial growth factor receptor (EGFR), and enhance POMC transcription, cell proliferation, and tumor growth." (PMID 33986726, 2021). "Moreover, in three tumor cell cultures, a 30–50% decrease in POMC messenger expression was identified, probably related to POMC promoter and transcriptional factors inhibition." (PMID 33363514, 2020). "In addition to the potent antiproliferative effect, tumor shrinkage was observed in 20% of the TBR-760–treated POMC KO mice with a mean volume reduction of 45%." (PMID 32591776, 2020). "POMC has a role in tumor development, by promoting epithelial–mesenchymal transition (EMT)." (PMID 33034614, 2020). "In view of the nuclear localization of mutant USP8 it remains to be determined whether USP8 also impinges more directly on tumor formation and POMC transcription in the nucleus." (PMID 31845722, 2019). "Moreover, immunoblot analysis revealed that the protein levels of Bax and LC3-ΙΙ in Ad-POMC-infected tumor tissues were higher than that in Ad-GFP-infected group." (PMID 30062060, 2018). "Using AtT20PL, a clone of the AtT20 mouse corticotroph tumor cells stably transfected with rat POMC 5′ promoter-luciferase fusion gene, PACAP and VIP were found to increase the POMC promoter activity and expression via a PKA-independent intracellular signaling pathway." (PMID 28223965, 2017). "However, there were few positive colored areas and even fewer buff-colored cells in the model group mice compared with the control group mice, the expression of β-END, POMC and μ-OR protein in the tumor tissues were significantly reduced (P < 0.01)." (PMID 28002791, 2017). "Results from the in vivo studies suggested that tumours post-radiation have acquired phenotypic characteristics that differ from untreated tumours and that these changes were coupled with a decrease in POMC biomarker secretion and expression and an increase in N-Cadherin." (PMID 26848743, 2016). "Therefore POMC shows a markedly differing relationship with tumour volume in untreated versus irradiated tumours." (PMID 26848743, 2016). "POMC gene expression was also decreased in the 20Gy IR tumours." (PMID 26848743, 2016). "Our aim was to determine whether POMC could act as a biomarker of tumour burden after irradiation treatment or if it is altered as a consequence of irradiation resistance, using the same murine model as previously established." (PMID 26848743, 2016).
tumor (continued). "However, tumours exposed to 2Gy/day for ten days displayed less and distinctly heterogeneous POMC staining within viable cell regions." (PMID 26848743, 2016). "However terminal POMC concentrations were lower than those in untreated animals even though all animals had been maintained until the tumours reached the same size." (PMID 26848743, 2016). "If this translated to patients, it would influence how well POMC could be used because by the time a relapsed tumour given radiotherapy is big enough to be detected by POMC, it could be beyond the size for which an alternative intervention might be useful." (PMID 26848743, 2016). "Moreover altered POMC promoter methylation has been observed in different tumor cell-lines, which was accompanied by changes in POMC gene expression." (PMID 22438814, 2012). "Thus the combination of a direct assay for the ACTH precursors and the panel of SCLC cell lines provides a valuable in vitro model for the expression of POMC in human tumours." (PMID 2553086, 1989). "However, this phosphoproteomics analysis also detected GH and POMC in NF-PitNET groups; this might be due to contamination of normal pituitary tissue during the tumor removal procedure." (PMID 34571875, 2021). "Aggressive EAS, can be associated with high POMC/ACTH ratio since the tumor tissue may secrete precursors that are not detected in conventional ACTH assays." (PMID 32903471, 2020). "Moreover, POMC, Tpit, and NeuroD1 mRNA showed higher expression in the tumor tissue than NFA, but lower expression than CD, suggesting that expression of 2 types of transcriptional factors might be associated with clinical manifestation." (PMID 28865461, 2017). "However, it is important to consider that POMC measurement may prove misleading for the majority of patients who have had irradiation and relapsed, because the circulating concentrations of POMC produced by the primary tumour remain suppressed." (PMID 26848743, 2016). "The treatment using a MEK inhibitor binimetinib, both in vitro and in vivo, inhibited the corticotroph tumor cell proliferation, POMC transcription, and ACTH secretion, rendering it a possible candidate for Cushing’s disease treatment." (PMID 37109772, 2023). "Ectopic ACTH expression and infiltration of CD3+, CD4+, CD8+, and CD20+ lymphocytes were observed in the tumor tissues and circulating anti-POMC antibodies were detected specifically in the patient’s serum." (PMID 38035072, 2023). "Gefitinib, a tyrosine kinase inhibitor targeting EGFR, attenuated POMC expression and ACTH secretion in human and canine corticotroph tumor cell cultures." (PMID 36672445, 2023). "It is worth noting that many genes were dramatically upregulated specifically in ACTH+&CRH + pheochromocyte when compared with the other tumor cell types, such as GAL, POMC, PNMT, and CARTPT." (PMID 34905486, 2021). "To validate this finding, we performed additional IHC staining experiments on paraffin-embedded serial slices with similar tissue regions from the tumor specimen esPHEO_T3 using antibodies against CgA, ACTH, POMC, CRH, TH, and GAL." (PMID 34905486, 2021). "In primary ACTH-secreting tumor cells we verified those findings and, interestingly, mutant tumor cells exhibited more sensitivity towards 17-AAG in terms of cell viability and POMC transcription." (PMID 33537004, 2020). "Given the strong antiproliferation effects of TBR-760 observed in POMC KO mice, as well as the observed tumor shrinkage, it is plausible that these same pathways are also activated and contribute to the response to TBR-760 in the POMC KO mouse." (PMID 32591776, 2020). "Cinobufagin exerts immunological analgesic effects by increasing the activity of the proopiomelanocortin (POMC)/β-endorphin (β-END)/μ-opioid receptor (μ-OR) pathway, which is activated by lymphocytes following tumor infiltration." (PMID 32595757, 2020).
tumor (continued). "Forced overexpression of TSP‐1 in a murine AtT20 pituitary corticotroph tumour cell line decreased corticotroph precursor hormone proopiomelanocortin (POMC) transcription and adrenocorticotropic hormone (ACTH) secretion." (PMID 31016850, 2019). "It has been shown that this drug regulates the expression of pro-opiomelanocortin (POMC), ACTH secretion, and tumor growth in corticotroph tumor mouse cell lines and in the nude mice experimental model, via inhibition of POMC transcription." (PMID 29881371, 2018). "Cinobufagin significantly improved β-END synthesis by increasing the expression of POMC, CTSL and stimulated the release of β-END by raising the levels of inflammatory chemokines in the tumor and adjacent tissues." (PMID 28002791, 2017). "We have shown that circulating levels of the neuroendocrine marker, POMC, correlate with a lower survival rate in patients with SCLC tumours." (PMID 26848743, 2016). "In summary, POMC biomarker expression and secretion were reduced in SCLC tumours which regrew after irradiation and in repeatedly irradiation (irradiation-primed) cells." (PMID 26848743, 2016). "In a murine corticotrope tumor cell line, retinoic acid has been shown to reduce ACTH secretion and pro-opiomelanocortin (POMC) synthesis." (PMID 23673515, 2013). "On the other hand, a decrease in eigenvector centrality indicates that a gene is connected to less influential or weakening genes, possibly resulting in lower relative influence scores or reduced significance in the network, such as ANXA1, GNB3, POMC, GPER1, and TIMP1 in tumor samples." (PMID 40626556, 2025). "Given the tumor’s poor differentiation, we hypothesize it may express POMC but fail to process it into ACTH, thereby inducing anti-POMC antibodies that attack pituitary corticotrophs." (PMID 41261694, 2025). "Indeed, it has been reported that Lapatinib, a TKI for corticotroph tumor cells, reduces ACTH production by decreasing the mRNA expression level of proopiomelanocortin (POMC)." (PMID 39473682, 2024). "Since melanocytes expressed MC1R and POMC—which can affect also endogenously MC1R and other MC receptors—rational combination of targeting peptides of MSH and POMC peptides can provide much higher inhibition of the tumor." (PMID 38256168, 2024). "In addition, it was shown that PRKCD silencing increases POMC and ACTH expression demonstrating that not only PRKCD exhibits tumor suppressing activities, but also regulates ACTH secretory mechanisms." (PMID 37233978, 2023). "Interestingly, the LCNEC tumor tissues exhibited ectopic ACTH expression, and an autoimmune antibody against POMC was identified in her serum." (PMID 38035072, 2023). "It was also demonstrated that COUP-TFα, which inhibits the POMC response to RA, was only expressed in normal ACTH-secreting pituitary cells but not in corticotroph tumor cells, potentially enhancing the ATRA actions in CD." (PMID 32272677, 2020). "In murine corticotroph tumor cells, direct binding of an LXR/RXR heterodimer to a POMC promoter DR4 motif (-73 AGGAAGGTCA CGTC CAAGGCTCA -52) was demonstrated, where LXRα specifically induced POMC transcription." (PMID 32272677, 2020). "In addition to its anti-proliferative effect, rosiglitazone inhibited POMC transcription and ACTH secretion in both primary human corticotroph tumor cultures and AtT20 cells." (PMID 32272677, 2020). "In ectopic ACTH-secreting tumor xenografted mice, R-roscovitine similarly suppressed POMC/ACTH secretion, but it did not alter tumor proliferation in DMS79 cells." (PMID 30147673, 2018).
tumor (continued). "This tumor entity is immunopositive for Tpit and expresses different POMC precursor proteins but does not secrete ACTH; moreover, genes related to ACTH synthesis are differently expressed in comparison with ACTH-secreting CAs2,69." (PMID 30228864, 2018). "The available transgenic mouse lines that are commonly used to phenotype POMC and NPY neurons (POMC-eGFP and NPY-eGFP mice, eGFP: enhanced green fluorescent protein) cannot be used as tumor recipients for our model because of an incompatible genetic background." (PMID 28475119, 2017). "We found that POMC was significantly reduced in resistant cells in vitro and in vivo and was not a good predictor of tumour regrowth after irradiation." (PMID 26848743, 2016). "Even more striking, when subcutaneous DMS 79 tumours were irradiated for 10 consecutive days at 2Gy/day, POMC did not mirror tumour re-growth (r = 0.35)." (PMID 26848743, 2016). "Four patients had POMC concentrations greater than 100 pmol L−1, considered to be the cut‐off for diagnosing POMC‐secreting tumours, with none in the control group." (PMID 26286459, 2015). "However, it is still possible that we might miss small populations of tumor cells that express ACTH and POMC." (PMID 40729185, 2023). "Beyond the rapid in vivo clearance of the pure SST analogue, the reasons why the pure DA and SST agonists inhibit NFPA cell proliferation in vitro but do not have a significant effect on tumor growth in the POMC KO mice is unknown." (PMID 32591776, 2020). "However, mechanisms for corticotroph-specific tumor induction by EGFR or for EGFR upregulation of ACTH/POMC expression have not been clearly elucidated." (PMID 30147673, 2018). "Using the small molecule E2F inhibitor HLM006474, originally developed as a therapy for melanoma, we showed dose-dependent suppression of POMC mRNA expression in primary cultures of surgically resected Cushing tumor tissue, but no suppression of growth hormone used as a control." (PMID 30147673, 2018). "However, analysis of individual tumor cultures revealed that dexamethasone failed to inhibit POMC in some 20 % and even induced a paradoxical increase in POMC scattering of tumors." (PMID 27220856, 2017). "These tumor cells expressed POMC peptides, but not other pituitary hormones." (PMID 25136513, 2014). "When tumor or inflammation occurs, immune cells from the peripheral recycling system access these locations to release POMC, which can be processed by proteases to form peptide hormones and factors, such as β-END, adrenocorticotropic hormone (ACTH), and alpha melanocyte stimulating hormone (α-MSH)." (PMID 24187573, 2013). "Our integrated analysis suggested POMC-expressing chromaffin cells may represent the cellular source of ectopic ACTH production and revealed a transcriptional signature involving metabolic activation and immune modulation that might contribute to tumor progression." (PMID 42074262, 2026). "Western blot analysis of the tumor and metastases revealed the presence of a high-molecular-weight precursor possibly POMC (at 30 kDa) but not ACTH (normally 4.5 kDa)." (PMID 32903471, 2020). "However, this scenario was not effective in our pancreatic ACTH-secreting tumor sample, where the absence of TBX19 and PITX1 overexpression points to alternative mechanisms driving the expression of POMC." (PMID 40002253, 2025). "Interestingly, the anti-corticotroph antibody recognized proopiomelanocortin (POMC) and those two patients exhibited ectopic ACTH expression in the tumor, while the patients without anti-corticotroph antibody did not." (PMID 33977343, 2021). "Likewise, neither cachectic tumor-bearing rats, nor LPS-treated rats did demonstrate changes in hypothalamic or ARC mRNA expression of POMC." (PMID 20953376, 2010).